STAT3 (signal transducer and activator of transcription 3)
Diseases named in the same sentence as STAT3 in open-access papers (continued):
Sharing a sentence is not in itself a finding about the gene and the disease.
prostate carcinoma (continued). "The apoptotic effects of ursolic acid against PC3 cells are mediated by the downregulation of Bcl-2, whereas its antitumor effects in prostate cancer growth in nude mice were associated with the suppression of NF-κB and STAT3 pathways." (PMID 33920405, 2021). "In line with the animal studies, it was shown in prostate cancer patients that loss of STAT3 and ARF correlated with increased risk of tumour recurrence." (PMID 34047814, 2021). "The use of STAT3 inhibitors in prostate cancer limited tumor-associated MDSCs and inhibited interleukin-1β (IL-1β), IL-10 and IL-6 synthesis by monocyte cultures." (PMID 32488850, 2020). "The IL-6/Janus kinase (JAK)/STAT3 pathway is aberrantly hyperactivated in many types of cancer, including prostate cancer, and such hyperactivation is generally associated with a poor prognosis." (PMID 32824865, 2020). "Reduces ARs with the F876L mutation in DU-145 and C4–2 cells, and destroy prostate cancer stem/progenitor (S/P) cell invasion through the alteration of EZH2/STAT3 signaling in mice with CWR-22Rv1 CD133+ S/P xenografts." (PMID 31801262, 2019). "In fact, it was shown that AR loss in prostate cancer cells favors stem-like phenotype and triggers IL-6 production, which in turn activates Stat3." (PMID 31366128, 2019). "In prostate cancer, both STAT3 and STAT5 have been associated with castration-resistant disease and proposed as therapeutic targets." (PMID 31557897, 2019). "In fact, Siltuximab was associated with increased tumor cell proliferation in prostate cancer, despite STAT3 dysregulation being frequently observed." (PMID 31842362, 2019). "HFD increases the risk of developing BPH and prostate cancer through an influence on the NF-kB and Stat-3 signaling pathways." (PMID 31412319, 2019). "Upregulation of STAT3 is implicated in prostate cancer and specifically in androgen-independent prostate cancers." (PMID 31771198, 2019). "The aim of the current work is to elucidate the underlying apoptotic mechanism of LA in association with STAT3 and NF-κB signaling in breast and prostate cancer cells." (PMID 31248140, 2019). "In a recent study, the noncanonical β-catenin-independent WNT pathway, represented by WNT5, FZD2, FYN, and STAT3, was found to be associated with high-risk prostate cancer." (PMID 31530281, 2019). "Reduces ARs with the F876L mutation in DU-145 and C4-2 cells, and destroys prostate cancer stem/progenitor (S/P) cell invasion through the alteration of EZH2/STAT3 signaling in mice with CWR-22Rv1 CD133+ S/P xenografts." (PMID 31801262, 2019). "In conclusion, our findings have demonstrated that ginsenoside Rh2 induces prostate cancer DU145 cells apoptosis through up-regulation of PPAR-delta expression which is associated with p-STAT3 up-regulation and ROS/superoxide induction." (PMID 29541400, 2018). "Considerable evidence suggests that activated STAT3 pathway is implicated in the progression of prostate cancer." (PMID 28783760, 2017). "PC3 cells are a prostate cancer cell line bearing a STAT3 whole-gene-deletion mutation on chromosome 1736." (PMID 28004755, 2016). "Stat3 is one of the prominent members among the transcription factors to regulate c-Myc and is linked with 5-lipoxygenase activity in prostate cancer cells." (PMID 25875826, 2015). "Our report shows, for the first time, that HGFL provides a survival advantage to prostate cancer cells through a Ron dependent pathway and that this effect is associated with the activation of STAT3 and Bcl2." (PMID 24980820, 2014). "In an examination of downstream signaling events associated with increased prostate cancer survival, a dramatic increase in STAT3 phosphorylation was observed in Ron expressing cells in presence of HGFL." (PMID 24980820, 2014).
prostate carcinoma (continued). "In this study we show that the STAT3 small molecule inhibitor Stattic caused S-phase accumulation at low-dose levels and led to massive apoptosis at a relatively high-dose level in prostate cancer cells." (PMID 25261365, 2014). "In harmony with this assumption, SOCS-3 expression has been shown to increase during development and progression of prostate cancer and enhances glioblastoma cell survival, its loss converting the anti-apoptotic function of STAT-3 into pro-apoptotic." (PMID 24593195, 2014). "In this study, we evaluated the anti-tumor activity of scoparone against DU145 androgen-independent prostate-cancer cells and found that its molecular mechanisms of action are associated with inhibition of STAT3 activity." (PMID 24260381, 2013). "The region 17q21 containing STAT3 was reported associated with prostate cancer in the Caucasian population." (PMID 23668334, 2013). "While these studies are just an initial exploration of the underlying mechanisms of STAT3 effects in prostate carcinoma cell invasiveness, they do suggest some molecular effectors." (PMID 16804520, 2006). "STAT3 pathway activation is associated with the development and progression of prostate cancer." (PMID 40565712, 2025). "While STAT3 activation has been implicated in LL-37-mediated M2 polarization in prostate cancer." (PMID 40453717, 2025). "As an example, the tumor suppressor gene phosphatase and tensin homolog (PTEN) and oncogene signal transducer and activator of transcription 3 (STAT3) are known to be dysregulated in human prostate cancer and are linked to increased malignancy and a poor prognosis." (PMID 37009802, 2023). "Previous studies have shown expression of STAT3 and activated STAT3 (pSTAT3) within tumour cells to be associated with outcome in colorectal, pancreatic and prostate cancers; however, there is limited evidence in the literature exploring STAT3 expression within the stroma." (PMID 37199043, 2023). "Furthermore, IL-6/STAT3 signaling has been implicated in the conversion from androgen-sensitive to androgen-resistant prostate cancer via the recruitment of myeloid-derived suppressor cells (MDSCs)." (PMID 36010693, 2022). "However, certain studies have reported that the high p-STAT3 expression was closely linked to a favorable prognosis in several cancer types, including breast and prostate cancer." (PMID 35314590, 2022). "According to this evidence, the authors showed that PC3 cells (prostate cancer cell line bearing a STAT3 whole-gene-deletion mutation) had low mitochondrial membrane potential that increased significantly, together with ATP production, after Stat3 transfection." (PMID 34440160, 2021). "Thus, the novel apoptotic mechanism of CK in association with STAT3 and PD-L1 signaling was examined in prostate cancer cells." (PMID 34440920, 2021). "More precisely, osteolytic lesions of human prostate cancer show enriched pAKT levels in the tumor area and associated macrophages, whereas osteoblastic lesions were shown to possess higher phospho-signal transducer and activator of transcription 3 (pSTAT3) levels." (PMID 34064589, 2021). "Thus, in the current study, the apoptotic mechanism of CK in association with STAT3 and PD-L1 signaling via the upregulation of miR193a-5p was elucidated in prostate cancer cells." (PMID 34440920, 2021). "AR had been demonstrated to reduce cancer stemness by repression of CD44 and SOX2, on the contrary, loss of AR expression could upregulate STAT3 expression and lead to promote development of cancer stemness in prostate cancer cells." (PMID 32365531, 2020). "Uncovering the underlying mechanism for CCL5-induced STAT3 activation might provide potential therapeutic targets for prostate cancer." (PMID 32300100, 2020). "Furthermore, the cytoprotective effect of HSP27 was attenuated by STAT3-reduced expression, underlying the importance of this pathway in prostate cancer." (PMID 31861612, 2019).
prostate carcinoma (continued). "STAT3, as a critical transcription factor, was highly phosphorylated in tumorigenesis and the level of phosphorylation was associated with worse prognosis in several cancers, including prostate cancer, HCC, and pancreatic cancer." (PMID 31438989, 2019). "Similarly, the regulation of CCL2 by STAT3 was also reported in prostate cancer cells and cancer-associated fibroblasts." (PMID 31781676, 2019). "STAT3 activation is associated with poor clinical outcome in prostate cancer patients." (PMID 31143708, 2019). "In this study, we first investigated whether constitutive activation of STAT3 protein is associated with prostate cancer in vivo." (PMID 25261365, 2014). "This phenomenon implies STAT3 is implicated in prostate cancer." (PMID 24205155, 2013). "Stat3 has been implicated in the promotion and progression of human prostate cancer." (PMID 22454635, 2012). "Therefore, therapeutic agents targeting STAT3 may be promising for prostate cancer patients exhibiting EAF2 deficiency." (PMID 39588149, 2024). "However, the activation status of STAT3 has been reported to be inversely associated with the progression of distant metastases in prostate cancer, whereas conflicting reports suggest that it is an effective prognostic marker for prostate cancer." (PMID 36010693, 2022). "Besides, increasing the stabilization of STAT3 through SOCS-1 or SOCS-2—both of which are downregulated by miR-155-5p or miR-194—promotes the spread of prostate cancer and is associated with the poor survival of patients with oral squamous cell carcinoma (OSCC)." (PMID 31952344, 2020). "In addition, zerumbone selectively inhibited the IL-6/JAK2/STAT3 pathway and blocked the prostate cancer-associated genes- cyclin D1, IL-6, COX2 (cytochrome c oxidase), and ETS Variant 1 (ETV1); thereby inducing cytotoxicity through G0/G1 cell cycle arrest and causing apoptosis." (PMID 30781671, 2019). "Since STAT3 is implicated in regulation of multiple cellular functions, its inhibition may also lead to down-regulation of processes leading to epithelial to mesenchymal transition in prostate cancer." (PMID 29214142, 2017). "Thus, STAT3 seems to function as an antiapoptotic factor, especially in numerous malignancies, where STAT3 is often constitutively active/phosphorylated and STAT3 activation has been associated with advanced stages of metastatic cancers such as prostate cancer." (PMID 21152185, 2011). "Silibinin, a flavanone with anticancer and hepatoprotective properties, inhibits STAT3 phosphorylation and encourages apoptosis in prostate cancer cells." (PMID 41596531, 2026). "It demonstrated strong cytotoxic activity compared to other fractions and clearly suppressed constitutive STAT3 activation in two human prostate cancer cell lines, DU145 and U266." (PMID 41596531, 2026). "Given the pivotal role of PRLR and JAK2/STAT3 signaling in hormone - dependent cancers, exploring their regulatory mechanisms in prostate cancer is vital for developing new treatments." (PMID 40978029, 2025). "The JAK2/STAT3 signaling pathway plays a crucial role in various cancers, including prostate cancer." (PMID 40978029, 2025).
prostate carcinoma (continued). "It was reported that the downregulation of hTERT was attributed to the suppression of transcriptional factors c-Myc, SP1, STAT3, and protein kinase B/Akt in prostate cancer cells and to both epigenic and genetic regulations in Panc-1 cells." (PMID 40281695, 2025). "Bioinformatics analysis was then performed to assess the relationship between the expression levels of PRLR, JAK2, and STAT3 genes and the survival of prostate cancer patients." (PMID 40978029, 2025). "Additional research suggests Ganoderma lucidum’s capacity to inhibit prostate cancer cell development and induce apoptosis through the Jak-1/STAT-3 signaling pathway." (PMID 40141325, 2025). "For instance, docetaxel-induced STAT3 activation promotes autophagy, contributing to chemotherapy resistance in castration-resistant prostate cancer." (PMID 40999385, 2025). "Collectively, our results identify a novel, ETV1‐dependent, oncogenic pathway in prostate cells and highlight the potential therapeutic outcome of coinhibition of EGFR and STAT3 in prostate carcinomas with ETV1 overexpression." (PMID 40808640, 2025). "Further, immunosuppressive TAMs secrete CCL5, which activates STAT3 signaling and promotes stem-like features and drug resistance in prostate cancer." (PMID 41228234, 2025). "Cell culture experiments demonstrated that apelin promotes integrin αvβ3-dependent prostate cancer migration by activating STAT3 and inhibiting miR-8070 via the MAPK pathway." (PMID 40612675, 2025). "In prostate cancer, sustained activation of the JAK2/STAT3 pathway is linked to tumor progression and poor patient prognosis." (PMID 40978029, 2025). "Targeting this pathway has emerged as a promising strategy to overcome resistance, with preclinical studies showing that inhibitors of STAT3/JAK2, such as AG490, can reduce STAT3-mediated AR activation and hinder prostate cancer cell growth." (PMID 41235005, 2025). "β-elemonic acid inhibits growth of human castration-resistant prostate cancer cells through the suppression of JAK2/STAT3/MCL-1 signal pathways." (PMID 40830747, 2025). "Much literature has reported that STAT3 has been implicated in promoting the oncogenesis and progression of prostate cancer, and we found that NCAPD3 not only promoted STAT3 expression but also regulated STAT3 phosphorylation." (PMID 39917394, 2025). "Consistently, prostate cancer cells secreted PD-1 in exosomes that enhanced the activity of MDSC by activating JAK/STAT3 signaling." (PMID 41281644, 2025). "In conclusion, we reveal that apelin increases integrin αvβ3 synthesis and promotes prostate cancer metastasis by activating STAT3 and inhibiting miR-8070 via the MAPK pathway." (PMID 40612675, 2025). "This suggests that Osthole inhibits the progression of prostate cancer by targeting the JAK2/STAT3 pathway." (PMID 40978029, 2025). "In prostate cancer, IL‐6‐induced STAT3 activation accelerates tumor progression, a condition clinically identified as neuroendocrine‐differentiated prostate cancer." (PMID 40166646, 2025). "The targeting of the STAT3 axis has been shown to reverse enzalutamide resistance in prostate cancer." (PMID 40427227, 2025). "Loss of STAT3 and ARF expression in patients with prostate cancer is correlated with an increased risk of disease recurrence and metastasis." (PMID 41104968, 2025). "P300 can mediate STAT3 acetylation in various malignancies, such as prostate cancer, HCC and breast cancer." (PMID 39778006, 2025). "In a study targeting Stat3 interference in RM1 prostate cancer cells, plasmid-based Stat3 specific short hairpin RNA (sh-Stat3) was delivered by nHA." (PMID 39776858, 2025). "Restoration of miR-26a-5p by EZH2 silencing can block the IL-6/STAT3 axis to inhibit prostate cancer growth." (PMID 40652273, 2025). "CPO inhibited constitutive STAT3 stimulation in multiple myeloma, breast, and prostate cancer cell lines, with MM cells exhibiting significant dose- and time-dependent effects." (PMID 38397437, 2024).
prostate carcinoma (continued). "The overexpression of IL-6 and JAK-1 is required for the STAT-3 activations that lead to prostate cancer proliferation and migrations." (PMID 39574470, 2024). "STAT-3 is frequently activated in prostate cancer, promoting tumor survival, growth, angiogenesis, and metastasis." (PMID 39574470, 2024). "IL-6 mediated JAK/STAT3 expressions regulate the proliferation and antiapoptosis that leads to prostate cancer metastasis and migration." (PMID 39574470, 2024). "The inhibition of CRIF1 prevents STAT3 activation, leading to the death of blastocysts and prostate cancer cells." (PMID 39682267, 2024). "Both the prostate cancer cell line DU-145 and the pancreatic cancer cell line MiaPaCa2 express activated STAT3 (Tyr705)." (PMID 38339286, 2024). "Is the dual‐edged nature of STAT3 derived from its ability to induce prostate cancer cellular senescence?" (PMID 39161800, 2024). "In the dorsolateral prostate (DLP) tissues of a TRAMP mouse model of prostate cancer, UA inhibited the activation of many pro-inflammatory mediators, such as NF-κB, STAT3, AKT, and IKKα/β phosphorylation." (PMID 38397437, 2024). "Janus kinase 2/signal transducer and activator of transcription 3 (JAK2/STAT3) signaling pathway plays an important role in a variety of cancers, including prostate cancer, hematological malignancies, and liver cancer." (PMID 38185661, 2024). "Morusin was reported to reduce STAT3 activity by inhibiting its phosphorylation, nuclear accumulation, and DNA binding activity-induced apoptosis in human prostate cancer cells." (PMID 39132159, 2024). "For example, AR degradation enhancer ASC-J9® suppresses prostate cancer cell invasion via modulating the STAT3 SUMOylation at Lys679 to alter the phosphorylation status of STAT3." (PMID 38245798, 2024). "6‐Shogaol downregulated the expression of STAT3‐ and NF‐κB‐regulated target genes such as cyclin D in prostate cancer cells." (PMID 39055196, 2024). "In this study, we investigated the role of CA in inhibiting the Interleukin-6 (IL-6)/Janus kinase (JAK)/Signal transducer and activator of transcription-3 (STAT-3) mediated suppression of the proliferation signaling in human prostate cancer cells." (PMID 39574470, 2024). "The natural product isoalantolactone mediates apoptosis and ER stress via the release of ROS and the downregulation of STAT3 in prostate cancer cells." (PMID 39765861, 2024). "The phosphorylation of Tyr 705 of STAT3 was also found to be inhibited by ISA in prostate cancer, breast cancer and melanoma." (PMID 39376605, 2024). "CA treatment on IL-6, JAK1, and p-STAT-3 (tyr705) expression in prostate cancer cells PC-3 were examined by western blotting." (PMID 39574470, 2024). "It has been reported that the atypical activation of the JAK2/STAT3 signaling pathway is an essential basis of prostate cancer." (PMID 39771106, 2024). "Keywords like microbiota, radiotherapy, gene expression, prostatectomy, IL-6, IL-1β, TNF-α, and STAT3 hold central positions within the prostate cancer domain, reflecting their frequent study." (PMID 39355131, 2024). "TAM-derived CCL5 promotes self-renewal of prostate cancer stem cells (PCSCs) and prostate cancer metastasis via activation of β-catenin/STAT3 signaling." (PMID 39199574, 2024). "STAT3 is an oncogenic transcription factor, constitutively activated in many human cancers, including prostate cancer, and activated by phosphorylation at Tyr705 in response to various signals such as cytokines and growth factors." (PMID 39590337, 2024). "Previous studies have demonstrated that the JAK2/STAT3 pathway regulates PD-L1 expression in various cancers, including head and neck squamous, lung, gastric, and prostate cancers." (PMID 39781272, 2024). "In prostate cancer, it has been shown that Linc00467 can promote the expression of STAT3 by acting on miR-494-3, which in turn promotes the malignant progression of prostate cancer and its transformation to NEPC." (PMID 39655078, 2024).